STPG1 (sperm tail PG-rich repeat containing 1)
Description:
May positively contribute to the induction of apoptosis triggered by O(6)-methylguanine.
Synonyms: MAPO2; C1orf201; FLJ33340
Tractability: No criterion of Open Targets' tractability assessment is met for any kind of drug.
Gene: Protein-coding gene on chromosome 1 (24,355,886 to 24,416,934, reverse strand). Ensembl gene ENSG00000001460.
Subcellular location: Cytoplasm; Nucleus
Subcellular location (Human Protein Atlas): Nucleoplasm
Gene Ontology:
Biological process: positive regulation of apoptotic process; positive regulation of mitochondrial membrane permeability involved in apoptotic process
Cellular component: cytoplasm; nucleus
Genetic constraint (gnomAD): Loss-of-function variants: 24 observed, 31 expected, observed/expected ratio (o/e) 0.77, 90% interval 0.56 to 1.09. The upper end of that interval is the gene's LOEUF score, 1.09, which puts it in group 4 of 6, group 1 being the genes least tolerant of losing a copy. Missense variants: 339 observed, 368.49 expected, observed/expected ratio (o/e) 0.92, 90% interval 0.84 to 1.01. Synonymous variants: 128 observed, 139.85 expected, observed/expected ratio (o/e) 0.92, 90% interval 0.79 to 1.06.
Homologues: Orthologues: chimpanzee STPG1 (99% identical), macaque STPG1 (95% identical), pig STPG1 (84% identical), dog STPG1 (80% identical), rabbit STPG1 (80% identical), guinea pig STPG1 (76% identical), mouse Stpg1 (71% identical), rat Stpg1 (71% identical), tropical clawed frog stpg1 (47% identical), zebrafish stpg1 (38% identical). Paralogues in human: STPG2 (22% identical), CIMAP1C (13% identical), CIMAP1A (13% identical), CIMAP1B (12% identical), CIMAP1D (11% identical).
Diseases named in the same sentence as STPG1 in open-access papers:
STPG1 is named in the same sentence as 6 diseases in open-access papers, as found by Europe PMC text mining. Sharing a sentence is not in itself a finding about the gene and the disease. The quoted sentences say what the papers report.
endometrial cancer (1 paper, 2020). Primary or metastatic malignant neoplasm involving the endometrium (mucous membrane that lines the endometrial cavity). "STPG1 is found with few traces from existing studies, but shows to be a prognostic marker in endometrial cancer (favorable) and renal cancer (favorable) from The Human Protein Atlas portal." (PMID 33194647, 2020).
gastric cancer (1 paper, 2022). A primary or metastatic malignant neoplasm involving the stomach. "Our study further demonstrated the function of STPG1 on T cell activation after coculture with gastric cancer cells." (PMID 35379170, 2022). "After the transfection of sh-ThPOK#1/2, the luciferase activity of the STPG1 promoter was reduced in gastric cancer cells." (PMID 35379170, 2022). "ThPOK inhibits gastric cancer cell viability and increases T cell activation by inducing STPG1 to inactivate the ERK pathway." (PMID 35379170, 2022). "The result of CCK-8 assay indicated that overexpressed STPG1 suppressed the viability of gastric cancer cells." (PMID 35379170, 2022). "The CCK-8 assay showed the decreased gastric cancer cell viability after the transfection of STPG1 overexpression vectors." (PMID 35379170, 2022). "STPG1 upregulation also exerted inhibitory effects on gastric cancer cell viability and T cell activation." (PMID 35379170, 2022). "The result of RT-qPCR analysis indicated that STPG1 expression was lower in the tissues of gastric cancer patients than adjacent normal tissues." (PMID 35379170, 2022). "Our study has demonstrated that both ThPOK and STPG1 inactivated the ERK signaling in gastric cancer cells." (PMID 35379170, 2022). "ThPOK inhibited gastric cancer cell viability and promoted T cell activation by transcriptionally inducing STPG1 to inactivate the ERK signaling." (PMID 35379170, 2022). "Silencing of STPG1 rescued the suppressive effect of ThPOK overexpression on the viability of gastric cancer cells." (PMID 35379170, 2022). "The result demonstrated that the low level of STPG1 was confirmed in cells of gastric cancer compared with the normal gastric mucosal cells (GES-1)." (PMID 35379170, 2022). "Moreover, a reduction in the mRNA and protein levels of STPG1 was observed in gastric cancer cells after the transfection of sh-ThPOK#1/2." (PMID 35379170, 2022). "Moreover, STPG1 overexpression was also found to enhance T cell activation after coculture with gastric cancer cells." (PMID 35379170, 2022). "STPG1 expression was also at a low level in the tissues and cells of gastric cancer." (PMID 35379170, 2022). "The mRNA and protein expression of STPG1 was positively modulated by ThPOK in gastric cancer cells." (PMID 35379170, 2022). "The overexpression efficiency of STPG1 in gastric cancer cells was confirmed by RT-qPCR." (PMID 35379170, 2022). "The function of STPG1 on gastric cancer cell behaviors was also explored." (PMID 35379170, 2022). "ThPOK positively regulated the mRNA and protein levels of STPG1 in gastric cancer cells." (PMID 35379170, 2022). "The low expression of STPG1 was also confirmed in the tissues and cells of gastric cancer." (PMID 35379170, 2022). "Additionally, ThPOK and STPG1 were revealed to inactivate the ERK pathway in gastric cancer cells." (PMID 35379170, 2022). "Thus, ThPOK positively regulated STPG1 expression in gastric cancer cells." (PMID 35379170, 2022). "The viability of gastric cancer cells and the proliferation ability of CD3+ T cells as well as the ratio of IFN-γ+ T cells in response to ThPOK overexpression and STPG1 knockdown were evaluated using CCK-8 assays and flow cytometry analyses, respectively." (PMID 35379170, 2022).
uveal melanoma (1 paper, 2022). A melanoma derived from melanocytes of the uveal tract. "A previous study has built a ten-gene signature including STPG1, and identified that this signature is correlated with the survival and immune infiltrating in uveal melanoma." (PMID 35379170, 2022).
STPG1 also shares sentences with these, for which no sentence is quoted: cancer (1 paper); renal carcinoma (1); tumor (1).